MAP3K1 (mitogen-activated protein kinase kinase kinase 1)
Diseases named in the same sentence as MAP3K1 in open-access papers (continued):
Sharing a sentence is not in itself a finding about the gene and the disease.
glioma (continued). "Moreover, elevated coexpression of TRIB2 and MAP3K1 was significantly correlated with a poor prognosis and indicated therapeutic resistance in glioma." (PMID 31318172, 2020). "Furthermore, to assess the prognostic roles of the combined expression of TRIB2 and MAP3K1 in glioma, we obtained the following four combinations using 91 tumor samples according to the IHC expression levels: TRIB2High/MAP3K1High, TRIB2High/MAP3K1Low, TRIB2Low/MAP3K1High, and TRIB2Low/MAP3K1Low." (PMID 31318172, 2020). "The nuclear-enriched lncRNA NEAT1 has been characterized as an oncogenic driver in gliomas, facilitating glioma stem cell proliferation via the NEAT1/let-7g-5p/MAP3K1 signaling axis." (PMID 41149459, 2025). "There was a significant correlation between the protein levels of MAP3K1 and the WHO grade of glioma, as indicated by correlation analysis of MAP3K1 IHC staining with clinicopathologic parameters." (PMID 39443331, 2024). "We found that patients with glioma and lower expression of TRIB2 or MAP3K1 exhibited prolonged overall survival compared with patients with glioma and higher TRIB2 or MAP3K1 expression." (PMID 31318172, 2020). "The data indicated that TRIB2 and MAP3K1 were likely to be enriched in GBM and grade III glioma (TRIB2High/MAP3K1High samples accounted for 72.09% in GBM and 63.16% in grade III glioma) compared with grade I and grade II glioma." (PMID 31318172, 2020). "IHC was performed on 91 glioma samples to analyze the expression of TRIB2 and MAP3K1, and three brain tissues from epilepsy surgery were used as negative controls." (PMID 31318172, 2020). "MAP3K1 knockdown can enhance TMZ‐induced proliferation inhibition and death of glioma cells." (PMID 39443331, 2024). "KEGG pathway analysis in conjunction with logFC showed that the cell cycle, glioma, ECM‐receptor interaction, and MAPK signalling pathway might be regulated by MAP3K1 in glioma." (PMID 39443331, 2024). "In addition, the patients with glioma were divided into two groups according to the GIS of TRIB2 and MAP3K1 expression." (PMID 31318172, 2020). "The IHC results showed that TRIB2 was predominantly expressed in the nucleus, and MAP3K1 was enriched in the cytoplasm and cytomembrane of glioma cells, while no significant staining was observed in the nontumor tissues." (PMID 31318172, 2020). "Interestingly, our survival analysis showed that patients with glioma and increased expression of TRIB2 and MAP3K1 exhibited worse responses to TMZ and radiotherapy." (PMID 31318172, 2020). "The results showed a significant increase in TRIB2 and MAP3K1 in the glioma samples compared with the nontumor samples." (PMID 31318172, 2020). "Moreover, a combined increase in TRIB2 and MAP3K1 was observed in GBM and indicated a poor prognosis of patients with glioma." (PMID 31318172, 2020). "Similarly, we assessed the expression of TRIB2 and MAP3K1 in glioma/GBM by analyzing the TCGA (RNA sequencing) database, and the results demonstrated that TRIB2 and MAP3K1 were markedly increased in glioma tissues, especially GBM tissues, compared with nontumor tissues." (PMID 31318172, 2020). "Seventeen glioma samples and three nontumor tissues were collected for RNA purification, and the expression levels of TRIB2 and MAP3K1 were evaluated by qRT‐PCR." (PMID 31318172, 2020).
melanoma (9 papers, 2010 to 2024). A malignant, usually aggressive tumor composed of atypical, neoplastic melanocytes. "Map3k1 is amplified in a subset of human desmoplastic melanomas and was previously linked to melanoma progression by two, independent transposon-mediated mutagenesis screens conducted in the Tyr::CreER(T2) BrafCA model." (PMID 34210801, 2021). "Two TN and four TB melanomas contained mutations affecting conserved residues of the MAP3K1 RING domain." (PMID 34210801, 2021). "In vivo mutagenesis screening has identified MAP3K1 as a driver in the development of melanoma in mice." (PMID 34404765, 2021). "Specifically, we identify clustered Map3k1 and Flna mutations in TN and TB melanomas irrespective of UV-irradiation status." (PMID 34210801, 2021). "Interestingly, the predominant phosphorylated (activated) form of MAP3K1 in melanoma cells is 140 kDa, which is a known alternatively spliced form (NCBI website)." (PMID 33122628, 2020). "DMs also tend to have lower DNA copy number alterations than other melanoma subtypes; the few focal deletions that have been observed target CDKN2A and NF1, whereas amplifications affect EGFR, CDK4, MDM2, TERT, MAP3K1, MET, YAP1 and NFKBIE13." (PMID 30511391, 2019).
glioblastoma (8 papers, 2018 to 2024). The most malignant astrocytic tumor (WHO grade IV). "Furthermore, we investigated immune infiltration levels in glioblastoma (GBM) associated with various somatic copy number alterations (SCNAs) of MAP3K1." (PMID 39443331, 2024). "In Glioblastoma (GBM), Trib2 interacts with MAP kinase kinase kinase 1 (MAP3K1) and enhances resistance to temozolomide (TMZ) chemotherapy and radiotherapy." (PMID 33794905, 2021).
non-small cell lung carcinoma (8 papers, 2011 to 2025). A group of at least three distinct histological types of lung cancer, including non-small cell squamous cell carcinoma, adenocarcinoma, and large cell carcinoma. "Additionally, tumor cell-derived exosomes containing miR-770 can impede M2 macrophage polarization by targeting MAP3K1, thereby suppressing invasion in non-small cell lung cancer." (PMID 38655063, 2024). "Non-small cell lung carcinoma (NSCLC) cell-derived extracellular vesicular miR-770 has been confirmed to inhibit M2 macrophage polarization by targeting MAP3K1, which in turn prevents tumor invasion." (PMID 36405712, 2022).
prostate carcinoma (7 papers, 2005 to 2024). A carcinoma that arises from epithelial cells of the prostate gland. "Other gene members of the MAP (mitogen-activated protein) kinase pathway, including MAP3K1 and MAP3K7, have been shown to have recurrent deletions in prostate cancer." (PMID 28423598, 2017).
colorectal cancer (6 papers, 2017 to 2025). A primary or metastatic malignant neoplasm that affects the colon or rectum. "For instance, in colorectal cancer (CRC), up-regulation of MAP3K1, MAP3K4, MAP3K7, and MAP3K8 has been associated with tumor progression, activation of oncogenic signaling pathways, and poor prognosis, similar to findings in GC." (PMID 39901302, 2025).
gastric cancer (6 papers, 2014 to 2023). A primary or metastatic malignant neoplasm involving the stomach. "We performed Cox regression analyses to assess the association of MAP3K1 rs889312 genotypes on survival of gastric cancer patients in various genetic models." (PMID 24759887, 2014). "Kaplan-Meier survival analysis and Cox proportional hazard regression were used to analyze the association between MAP3K1 rs889312 genotypes and survival outcomes of gastric cancer." (PMID 24759887, 2014). "Association between MAP3K1 rs889312 polymorphism and survival outcomes of gastric cancer patients in various genetic models." (PMID 24759887, 2014). "In this study, we systematically investigated the association between the MAP3K1 rs889312 SNP and overall survival in a relatively large population of Chinese gastric cancer patients." (PMID 24759887, 2014). "Considering steroid hormone-mediated signaling pathways have an important role in the progression of gastric cancer, we hypothesized that MAP3K1 rs889312 may be associated with survival outcomes in gastric cancer." (PMID 24759887, 2014). "Considering the role of the MAP3K1 rs889312 SNP involved in the risk of BC, we therefore hypothesized that MAP3K1 rs889312 may also be associated with survival outcomes in gastric cancer, and thus may have the potential to serve as a prognostic marker for this disease." (PMID 24759887, 2014). "The hormone-dependent effect of MAP3K1 gene polymorphisms may explain sex-specific differences in gastric cancer (GC) risk." (PMID 36510163, 2022). "We genotyped MAP3K1 rs889312 using TaqMan in 884 gastric cancer patients who received subtotal or total gastrectomy." (PMID 24759887, 2014). "Interestingly, mutations in MAP3K1/MAP2K4 are more prevalent in breast, prostate, and stomach cancer, and less common in other types of cancers." (PMID 32886682, 2020).
pancreatic cancer (6 papers, 2011 to 2025). "Phosphoproteomic analyses following 51-106 treatment revealed that nucleophosmin (NPM1)T199 phosphorylation is decreased upon MAP3K1 inhibition and is associated with cell cycle regulation in pancreatic cancer cells." (PMID 40363807, 2025). "In pancreatic cancer patients, elevated levels of MAP3K1 have been associated with lymph node metastasis, and its overexpression is associated with poor survival." (PMID 40363807, 2025). "MAP3K1 kinase function has also been implicated in the growth, invasion, and migration of pancreatic cancer cells and expression of kinase-dead, MAP3K1-promoted cell death in pancreatic cancer cell lines." (PMID 40363807, 2025). "MAP3K1 is highly expressed in pancreatic cancer patients, and the metastasis of human pancreatic cancer cells is suppressed by a reduction in MAP3K1 activity." (PMID 39443331, 2024). "In pancreatic cancer, MAP3K1 is overexpressed and inhibiting MAP3K1 activity effectively suppresses the metastasis of pancreatic cancer cells." (PMID 39443331, 2024). "Thus, a selective MAP3K1 inhibitor has the potential to be developed as a pancreatic cancer therapeutic." (PMID 40363807, 2025). "Finally, α2β1 integrin and MAP3K1 expression were significantly up-regulated in pancreatic tumours and correlated with poor prognosis in pancreatic cancer patients." (PMID 39666682, 2024). "Finally, α2β1 integrin and MAP3K1 were significantly up-regulated in pancreatic tumours compared to healthy tissue and high expression of these genes correlated with reduced survival of pancreatic cancer patients." (PMID 39666682, 2024). "When RNA from pancreatic tumors was used, antisense intronic transcription was detected in three additional loci (ATF2, TGFBR2 and MAP3K1), which produced both sense and antisense messages." (PMID 22078386, 2011).
colon cancer (5 papers, 2013 to 2024). "In colon cancer, circ_0085315 adsorbs miR‐1200 to upregulate MAP3K1 and enhance cancer progression." (PMID 39502735, 2024).
hypospadias (5 papers, 2016 to 2021). Hypospadias is the displacement of the urethral meatus on the ventrum of the penis. "Mutations of MAP3K1 and ATF3 were also found to be associated with an increased risk of hypospadias." (PMID 31856834, 2019). "We also observed two MAP3K1 variants (p.M312L and p.A1443V) that recurred in multiple patients who presented with a diverse range of phenotypes (including CGD, PGD, hypospadias, and undervirilization)." (PMID 27899157, 2016). "In the case of MAP3K1, DHH, and ZFPM2 it is difficult to distinguish whether variants identified in patients categorized as isolated hypospadias expand the known mutation spectrum of these genes or whether these patients have underlying gonadal dysgenesis." (PMID 27899157, 2016).
gonadal dysgenesis (4 papers, 2016 to 2025). A congenital disorder characterized by the presence of extremely hypoplastic gonads preventing the development of secondary sex characteristics. "Mutations in NR5A1, DMRT1, and MAP3K1 are other leading causes, but together with mutations in the SRY gene, they explain less than 40% of all non‐syndromic forms of 46 XY gonadal dysgenesis." (PMID 40747867, 2025). "MAP3K1 mutations were first described in 2010 in two large families with 46, XY DSD in an autosomal dominant, sex‐limited pattern of transmission, as well as in 2 of 11 sporadic cases of 46, XY gonadal dysgenesis." (PMID 32986312, 2020).
Infertility (4 papers, 2013 to 2024). "Mutations in MAP3K1 have been associated with imperforate vagina, labor failure, infertility, and in Swyer syndrome, where genetic males appear to physically be females, in humans and mice." (PMID 38939530, 2024). "MAP3K1 kinase domain-deficient female mice exhibited an imperforate vagina, labor failure and infertility." (PMID 38501211, 2024). "Notably, females deficient in the kinase domain of MAP3K1 present with conditions such as imperforate vagina, labor failure, and infertility, highlighting the indispensable role of MAP3K1 in reproductive health." (PMID 38778305, 2024). "Specifically, MAP3K1 KD deficiency impairs the caudal MD elongation and fusion with the UGS during development, likely through MAPK–WNT signaling crosstalk, leading to imperforate vagina and infertility in adult females." (PMID 38501211, 2024).
Swyer syndrome (4 papers, 2023 to 2025). "Swyer syndrome may be caused by SRY mutation (10%–15%), FTHL17, STARD8, SOX9, MAP3K1, NR5A1, and desert hedgehog gene (DHH) mutation as well as other unidentified genes." (PMID 41163677, 2025). "Genomic alterations in MAP3K1 have been reported in diverse cancer types and the Swyer syndrome." (PMID 36980976, 2023). "Considering the risk of malignancy in gonads in patients with Swyer syndrome, the data suggest that some pathogenic variants (FTLHL17, DAX-1, DHH R124Q, del at 17q24.3) may be associated with a higher risk and some (STAR, STARD8, MAP3K1) with a lower risk of tumorigenesis." (PMID 38337479, 2024).
atherosclerosis (3 papers, 2020 to 2022). A disease characterized by the build-up of fatty material and calcium deposition in the arterial wall resulting in partial or complete occlusion of the arterial lumen. "Through analysis of the public database, seven hub genes (UQCR11, UBE2N, ADD1, TLN1, IRAK3, LY96, and MAP3K1) have recently been found to be strongly associated with familial hypercholesterolemia and contribute to a higher risk of atherosclerosis." (PMID 34895070, 2021). "Our study identified seven core genes (UQCR11, UBE2N, ADD1, TLN1, IRAK3, LY96, and MAP3K1) that are strongly linked to FH and lead to a higher risk of atherosclerosis." (PMID 32760426, 2020).
cardiac hypertrophy (3 papers, 2020 to 2025). "Previous studies have suggested that the expression of MAP3K1 plays a key role in cardiac hypertrophy and apoptosis by MEKK1-JNK pathway." (PMID 33281884, 2020). "Noticeably, a recent study established GXNT’s MEK-ERK1/2 inhibition in cardiac hypertrophy, while our study reveals how its compounds Sal B and Sen I synergistically target the upstream factor MAP3K1, providing greater mechanistic resolution of this herbal medicine's polypharmacology." (PMID 41015772, 2025). "Importantly, knockdown of MAP3K1 alone effectively attenuated cardiac hypertrophy to a similar extent as the drug combination, suggesting its role as a critical mediator through which Sal B and Sen I exert their therapeutic effects." (PMID 41015772, 2025). "Collectively, these findings reinforce the hypothesis that Sal B and Sen I synergistically attenuate cardiac hypertrophy via coordinated suppression of the MAP3K1 signaling pathway." (PMID 41015772, 2025). "Therefore, the role of MAP3K1 in pathologic cardiac hypertrophy requires further investigation." (PMID 41015772, 2025).
disorders of sex development (3 papers, 2011 to 2024). "Dominant missense variants of human MAP3K1 cause Disorders of Sex Development (DSDs, OMIM 613762, SRXY6), a sex-limited 46,XY gonadal dysgenesis phenotype with a partial or complete sex reversal to a female phenotype." (PMID 39062623, 2024). "Recently, cases of familial andspontaneous 46,XY disorders of sex development (DSD) have been attributed tomutations in the human gene encoding mitogen-activated protein kinase kinasekinase 1, MAP3K1, a component of the mitogen-activated protein kinase (MAPK)signal transduction pathway." (PMID 21559298, 2011).
psoriasis (3 papers, 2021 to 2025). An autoimmune condition characterized by red, well-delineated plaques with silvery scales that are usually on the extensor surfaces and scalp. "In our psoriasis hypothesis, we assume NEAT1 to be down-regulated while MAP3K1-2 and AKAP13-AS1 are normally expressed." (PMID 39337694, 2024).
acute leukemia (2 papers, 2025). A clonal (malignant) hematopoietic disorder with an acute onset, affecting the bone marrow and the peripheral blood. "BAALC binder of MAP3K1 and KLF4 (BAALC), a regulator of developing neuroectoderm tissues overexpressed in acute leukemia and GBM, and a target of SOX2 in differentiated GBM cells, was upregulated in HF2303 SDCs." (PMID 39919036, 2025).
deafness (2 papers, 2015 to 2024). An inherited or acquired condition characterized by the complete loss of the ability to hear from one or both ears. "Homozygosity for two different mouse Map3k1 variants results in profound deafness by nine weeks after birth." (PMID 39062623, 2024). "One example is two different recessive variants of mouse Map3k1 associated with syndromic deafness." (PMID 39062623, 2024). "Yet, two different recessive variants of mouse Map3k1 associated with deafness are consistent with our supposition that the genetic explanation for nonsyndromic deafness segregating in sibship A of Family PKDF1419 has been identified as c.4460G>A p.(Arg1487His) of MAP3K1." (PMID 39062623, 2024). "In one of the two sibships of this family, a novel homozygous recessive variant NM_005921.2:c.4460G>A p.(Arg1487His) in the kinase domain of MAP3K1 co-segregated with nonsyndromic deafness." (PMID 39062623, 2024). "We posit that MAP3K1 falls into this category of a ubiquitously expressed gene where subtle changes result in a focused phenotype, in this case, deafness." (PMID 39062623, 2024). "The goya mutation has led to the identification of a new sensorineural deafness locus and it is important to consider Map3k1 as a candidate gene for both dominant and recessive human deafness loci." (PMID 26542706, 2015). "MAP3K1 phosphorylates serine and threonine and functions in a signaling pathway where pathogenic variants of HGF, MET, and GAB1 were previously reported to be associated with human deafness DFNB39, DFNB97, and DFNB26, respectively." (PMID 39062623, 2024). "To date, a second family or a singleton with additional deleterious variants of MAP3K1 associated with deafness have not been ascertained by us or reported by others." (PMID 39062623, 2024). "In contrast to dominant variants of MAP3K1 associated with Disorders of Sex Development 46,XY sex-reversal, our computational modeling of the recessive substitution p.(Arg1487His) predicts a subtle structural alteration in MAP3K1, consistent with the limited phenotype of nonsyndromic deafness." (PMID 39062623, 2024). "It cannot be ruled out that the c.4460G>A p.(Arg1487His) of MAP3K1 variant is in linkage disequilibrium with a nearby real causal variant responsible for deafness in sibship A of Family PKDF1419." (PMID 39062623, 2024). "It cannot be ruled out that the c.4460G>A p.(Arg1487His) of MAP3K1 variant is in linkage disequilibrium with a nearby causal variant responsible for deafness in sibship A of Family PKDF1419." (PMID 39062623, 2024).
endometrial cancer (2 papers, 2022 to 2026). Primary or metastatic malignant neoplasm involving the endometrium (mucous membrane that lines the endometrial cavity). "Genomic analyses across >35 cancer types reveal MAP3K1 alterations at frequencies of <1-14%, highest in breast and endometrial cancers." (PMID 41972694, 2026).
esophageal cancer (2 papers, 2020 to 2023). A primary or metastatic malignant neoplasm involving the esophagus. "MAP3K1 promotes cell proliferation and invasion in esophageal cancer, and inhibits anoikis, thus playing a tumor-promoting role." (PMID 37114037, 2023).
hearing loss (2 papers, 2015 to 2024). "Optimistically, more families segregating hearing loss associated with additional recessive variants of MAP3K1 (or singletons) will come to light following this report." (PMID 39062623, 2024). "In addition, MAP3K1 is revealed as a new candidate gene for human sensorineural hearing loss." (PMID 26542706, 2015).